INTS14 (integrator complex subunit 14)
Description:
Component of the integrator complex, a multiprotein complex that terminates RNA polymerase II (Pol II) transcription in the promoter-proximal region of genes. The integrator complex provides a quality checkpoint during transcription elongation by driving premature transcription termination of transcripts that are unfavorably configured for transcriptional elongation: the complex terminates transcription by (1) catalyzing dephosphorylation of the C-terminal domain (CTD) of Pol II subunit POLR2A/RPB1 and SUPT5H/SPT5, (2) degrading the exiting nascent RNA transcript via endonuclease activity and (3) promoting the release of Pol II from bound DNA. The integrator complex is also involved in terminating the synthesis of non-coding Pol II transcripts, such as enhancer RNAs (eRNAs), small nuclear RNAs (snRNAs), telomerase RNAs and long non-coding RNAs (lncRNAs). Within the integrator complex, INTS14 is part of the integrator tail module that acts as a platform for the recruitment of transcription factors at promoters.
Synonyms: C15orf44; VWA9; DKFZP564O1664
Tractability: PROTAC: ubiquitination databases record sites on it.
Gene: Protein-coding gene on chromosome 15 (65,578,753 to 65,611,615, reverse strand). Ensembl gene ENSG00000138614.
Subcellular location: Nucleus
Subcellular location (Human Protein Atlas): Mitochondria; Nuclear bodies; Nucleoplasm; Nuclear membrane
Pathways (Reactome):
Gene expression (Transcription): RNA polymerase II transcribes snRNA genes
Gene Ontology:
Molecular function: protein binding
Biological process: regulation of transcription elongation by RNA polymerase II; RNA polymerase II transcription initiation surveillance; snRNA processing; snRNA 3'-end processing
Cellular component: INTAC complex; integrator complex; nucleus; nucleoplasm
Genetic constraint (gnomAD): Loss-of-function variants: 21 observed, 48.75 expected, observed/expected ratio (o/e) 0.43, 90% interval 0.3 to 0.62. The upper end of that interval is the gene's LOEUF score, 0.62, which puts it in group 2 of 6, group 1 being the genes least tolerant of losing a copy. Missense variants: 500 observed, 639.01 expected, observed/expected ratio (o/e) 0.78, 90% interval 0.73 to 0.84. Synonymous variants: 201 observed, 244.89 expected, observed/expected ratio (o/e) 0.82, 90% interval 0.73 to 0.92.
Homologues: Orthologues: chimpanzee INTS14 (100% identical), macaque INTS14 (99% identical), dog INTS14 (98% identical), guinea pig INTS14 (98% identical), pig INTS14 (98% identical), mouse Ints14 (98% identical), rabbit INTS14 (98% identical), rat Ints14 (97% identical), tropical clawed frog ints14 (89% identical), zebrafish ints14 (66% identical), Drosophila melanogaster IntS14 (36% identical).
Diseases named in the same sentence as INTS14 in open-access papers:
INTS14 is named in the same sentence as 9 diseases in open-access papers, as found by Europe PMC text mining. Sharing a sentence is not in itself a finding about the gene and the disease. The quoted sentences say what the papers report.
non-small cell lung carcinoma (2 papers, 2017 to 2024). A group of at least three distinct histological types of lung cancer, including non-small cell squamous cell carcinoma, adenocarcinoma, and large cell carcinoma. "Furthermore, INTS14/VWA9 was found to be upregulated in immortalized cells, cancer cells, and non-small-cell lung cancer tissues." (PMID 28468258, 2017). "INTS14 expression is increased in SV40-immortalized cells, lung cancer cells, and non-small cell lung cancer tissues." (PMID 38926181, 2024).
anemia (1 paper, 2023). A reduction in the number of red blood cells, the amount of hemoglobin, and/or the volume of packed red blood cells. "Anemia and folic acid deficiency diseases are associated with INTS14." (PMID 38200816, 2023).
liver cancer (1 paper, 2022). An epithelial or non-epithelial malignant neoplasm that arises from the liver. "MYC mRNA was highly expressed in the INTS14 mRNA high-expression group in prostate and liver cancer cell lines in the database, PC-3 cells (prostate cancer-derived cells) and HuH-7 cells (liver cancer-derived cells) were utilized for the following experiments." (PMID 35887071, 2022). "In further database analysis of human cancers, a higher expression of MYC mRNA was observed in the INTS14 mRNA high-expressing prostate and liver cancers." (PMID 35887071, 2022).
prostate adenocarcinoma (1 paper, 2022). "In the Prostate Adenocarcinoma (TCGA, Firehose Legacy) and Liver Hepatocellular Carcinoma (TCGA, PanCancer Atlas) datasets, MYC mRNA was highly expressed in the INTS14 mRNA high-expression group." (PMID 35887071, 2022).
cancer (4 papers, 2017 to 2022). A tumor composed of atypical neoplastic, often pleomorphic cells that invade other tissues. "INTS9, INTS11, INTS13, and INTS14 were mutated in very few cancer types, with a very low mutation rate." (PMID 28468258, 2017). "We also detected an interaction between the Drosophila C7orf26 ortholog and fly Integrator and observed co-essentiality between C7orf26 and INTS10, INTS13, and INTS14 in the Cancer Dependency Map (Data S2)." (PMID 35688146, 2022).
tumor (3 papers, 2022 to 2024). "The Mann–Whitney U test was used to compare the mRNA expression relationship between MYC and INTS14 or ERI2 in a dataset featuring each tumor type." (PMID 35887071, 2022).
INTS14 also shares sentences with these, for which no sentence is quoted: lung carcinoma (1 paper); prostate carcinoma (1); rhabdoid tumor (1).